TLR7 (toll like receptor 7)
Diseases named in the same sentence as TLR7 in open-access papers (continued):
Sharing a sentence is not in itself a finding about the gene and the disease.
infection (continued). "An explanation for the observed pattern of vulnerability has been proposed which is based on the concept of low sensitivity of the TLR7-signaling pathway at the time of infection as a common denominator of vulnerable patient groups." (PMID 35065665, 2022). "There was altered TNF-α release following TLR7/8 stimulation in untreated infection (p=0.024 at 1-month, p=0.055 at 12-months), but this function was restored following late ART initiation." (PMID 34630420, 2021). "IFN-α release trended lower following TLR7/8 stimulation in acute untreated infection compared to early ART individuals (p=0.076), but this too stabilised by 12-months post-infection." (PMID 34630420, 2021). "Taken together, our data demonstrate that although LCMV restrains early TLR7-mediated signalling, it primes differentiated MФ to enhance expression of their respective cytokine profiles and maintains levels of TLR7 expression early after infection." (PMID 33331816, 2021). "After 48 h of infection, we observed a predominant induction of both TLR7 and TLR3 expression (p < 0.001; Student’s t-test)." (PMID 34576716, 2021). "In contrast, 42.86% of TlR7 KO mice died within 40 days after infection, 42.86% of TLR7 KO mice died within 47-51 days, and 14.28% of TLR7 KO mice died within 73 days." (PMID 34692568, 2021). "IFN response to DENV infection is important in limiting the infection, possibly through triggering TLR7 after cell-to-cell contact with a member of the flavivirus." (PMID 34960061, 2021). "MIP-1α production upon infection with A. phagocytophilum was unaltered in TLR7-/- Hoxb8 neutrophils compared to WT cells." (PMID 33747981, 2021). "Meanwhile, the addition of the TLR3 inhibitor reduced the secretion of IFN-α and IFN-β 24 h post-infection, while the addition of the TLR7 inhibitor reduced the expression of these type I IFNs 48 h post-infection (p < 0.001; Student’s t-test)." (PMID 34576716, 2021). "Trypanosoma cruzi experimental infection in TLR-deficient mice showed that TLR2, TLR4, TLR7, and TLR9 play a role in host resistance." (PMID 34336720, 2021). "An in vitro infection with hMPV leads to increased expression of TLR7 and TLR8, with peaks at 12 hours p.i., followed by a decreased expression after this time point." (PMID 33809875, 2021). "Despite similar levels of Tlr7 on day 3 post H1N1 or H3N2 infection, gene expression levels remained heightened in aged lung on day 5 and 7 post H1N1." (PMID 34829979, 2021). "This study found that the expression of TLR4 and TLR7 increased obviously after infection, and the percentage of TLR7 expressing B cells was higher than that for TLR4 expressing B cells in the infected mice." (PMID 34788282, 2021). "To do so, we examined cytokine production and TLR7-mediated signalling at 1 h post-lymphocytic choriomeningitis virus (LCMV) Armstrong (ARM) infection." (PMID 33331816, 2021). "The percentages of CD19+ cells in TLR7 expressed mono-nuclear cells were significantly increased after infection." (PMID 34788282, 2021). "Accordingly, the importance of TLR7 in response to the infection with single-stranded RNA viruses was repeatedly demonstrated in mouse models." (PMID 33857267, 2021). "Other study using a transgenic mouse deficient for endosomal nucleic acid sensing TLRs (TLR3, TLR7 and TLR9) showed increased parasitism and bigger lesion after 6 weeks post infection." (PMID 34745100, 2021). "There was poor granuloma formation in the liver of the host, and the liver tissue was filled with eggs of S. japonicum, which suggests that the deletion of TLR7 reduces the formation of granulomas during infection." (PMID 34692568, 2021). "The results indicated that the proportion of TLR7-positive cells was markedly increased 5-6 weeks post infection (P < 0.05) and was more than 2-fold upregulated in infected mice." (PMID 34692568, 2021).
infection (continued). "Taken together, these data confirm that endosomal TLR2, TLR7 and MyD88 colocalize to Bb-containing phagosomes to facilitate recognition of bacterial ligands and early response to infection." (PMID 34000990, 2021). "Silencing MyD88 which is activated by TLR7 or silencing MAVS which is activated by MDA5 in microglia exposed to exosomes secreted by microglia during TMEV infection reduced the expression of type I interferons." (PMID 34485270, 2021). "The counts of MHCII+CD11C+ DCs in hepatic lymphocytes isolated from both naive and infected WT and TLR7 KO mice 5-6 weeks after infection were compared." (PMID 34692568, 2021). "In H1N1-infected animals, TLR7 RNA expression was significantly increased in the spleen 4 days after infection." (PMID 34530852, 2021). "IFN-γ was induced by SARS-CoV-2 48 h post-infection (p < 0.001; Student’s t-test) and reduced by the TLR7 inhibitor (p < 0.001; Student’s t-test)." (PMID 34576716, 2021). "In purified B cells, the expression of TLR4 and 7 increased significantly after infection (p < 0.05), especially the expression of TLR7 which increased nearly 3 times after infection." (PMID 34788282, 2021). "For example, our previous study found that the percentage of TLR7 expressed T lymphocytes from the mesenteric lymph node (MLN) of S. japonicum infected mice increased on week 6 post infection." (PMID 34788282, 2021). "Taken together, these results indicate that as early as 1 h post-infection, changes in cytokine secretion levels are detectable; therefore, we chose this time point for analysis of TLR7 responsiveness during very early LCMV infection in subsequent experiments." (PMID 33331816, 2021). "In koala H8 (KoRV-B-negative and KoRV-C-positive), TLR-7, -8, and -10 expressions were markedly higher than in koalas with endogenous infection only (KoRV-A)." (PMID 33915914, 2021). "Tlr7-/- mice infected with HSV-2 survived the infection compared to WT counterparts, and this was accompanied by transient reduction in viral titers at 3 days post-infection." (PMID 35058919, 2021). "seem to be not completely recognized, yet even though the results of this study suggest that TLR7 plays an important role in the infection of B. canis." (PMID 33829052, 2021). "The percentage of IFN-γ-secreting CD8+ T cells increased significantly after infection (P < 0.05), while it decreased significantly in infected TLR7 KO mice, as well as IL-2 and IL-6 (P7 < 0.05)." (PMID 34692568, 2021). "Our results suggested the importance of the role of TLR7 in the early stage of infection of B. canis." (PMID 33829052, 2021). "In mice, adjuvanting the protein with a TLR7/8 agonist formulation alum-3M-052 induces 100-fold higher neutralizing antibody titer and superior protection from infection compared to alum." (PMID 34117252, 2021). "Nevertheless, genetic studies from both mice and humans indicate a clear role for TLR7 infection in vivo." (PMID 33202596, 2020). "For TLR7, expression declined with increasing virus titer in all organs at early time post infection as virus titers peaked." (PMID 33230226, 2020). "In reverse, EVA71 infection down-regulates TLR7 and its downstream products in 16HBE cells, including MYD88, interferon regulatory factor 7 (IRF7), and the secretion of type I IFN, markers for activation of innate immune responses." (PMID 33298183, 2020). "CD4+ T cells were TCR-activated and treated with TLR7/8/9 ligands for 24 h before infection with NLENG1-IRES-eGFP virus." (PMID 31919342, 2020). "We generate 977 miRNA-sequencing profiles from primary monocytes from individuals of African and European ancestry following activation of three TLR pathways (TLR4, TLR1/2, and TLR7/8) or infection with influenza A virus." (PMID 32731901, 2020). "The 44 NHPs were infected intrarectally with SHIV and ART was initiated at day 7 post-infection and continued for 96–104 weeks before bNAb and TLR7 agonist administration." (PMID 32595636, 2020).
infection (continued). "This study identifies tRNA half-molecules as abundant TLR ligands which are upregulated upon infection by mycobacteria and activate TLR7." (PMID 33332353, 2020). "At 6 days after infection, the levels of Tlr7 and Tlr8 in both the brain (P < 0.0001) and the spinal cord (P < 0.01) were higher in WT-infected than in Y114A- or G32S-infected mice." (PMID 32047134, 2020). "A polymorphism in TLR7 (rs179008) is associated with increased viral loads and altered CD4 T cell counts during infection and is possibly associated with lower risk of transmission." (PMID 33202596, 2020). "To further explore the immunological impact of TV+TLR7 we performed ELISAs at week 4 after infection and prior to ART initiation, week 22 prior to vaccination, week 34 after priming with Ad48, week 52 after boosting with MVA, and 2 weeks prior to ATI." (PMID 33104758, 2020). "In a model of C. albicans infection, resistance to infection it was also correlated with the activation of TLR7 and the transcription factor IRF1." (PMID 33194839, 2020). "In view of the severe reduction in in vivo production of chemokines and cytokines observed in TLR7/9/13 triple KO mice during infection, it was of interest to analyze the ability of macrophages from these mice to respond to pneumococci." (PMID 32209688, 2020). "TLR7 recognizes viral ssRNA and induces production of type I IFNs and proinflammatory cytokines during infection by IAV, vesicular stomatitis virus, and WNV and in response to transfected human immunodeficiency virus (HIV)-1 ssRNA." (PMID 32751803, 2020). "Both Myd88−/− and TLR7−/− mice exhibited higher viral loads than WT mice at late times post-infection." (PMID 30909385, 2019). "We observed that induction of IFN-β expression after infection was also significantly reduced in TLR7−/− mice as compared to Wt controls." (PMID 30930901, 2019). "Further clinic investigations are warranted to define the roles of TLR7 in human host infection of S. japonicum." (PMID 31930147, 2019). "We first s.c. infected Wt and TLR7−/− mice and compared their survival over the course of infection." (PMID 30930901, 2019). "After day 6 of infection, TLR7−/− mice developed signs of hind limb paralysis and by day 9 post infection (p.i.), 40–50% had succumbed to infection as compared to Wt mice." (PMID 30930901, 2019). "Here we demonstrate that the experimental infection of mouse-isolated neutrophils with CHIKV resulted in NETosis (NETs release) through a mechanism dependent on TLR7 activation and reactive oxygen species generation." (PMID 32082301, 2019). "During H7N9-NS1-103F/106M infection, however, we observed that TLR7 became repressed although RIG-I and key regulators of cytokines production and antiviral responses were not rescued." (PMID 31572308, 2019). "Our observations revealed that the induction of apoptosis upon EV71-infection was significantly reduced in TLR7-/- mice." (PMID 31730654, 2019). "First, we show that activation of major innate immunity pathways, such as TLR1/2, TLR4 and TLR7/8, and infection with a live strain of IAV increase isoform diversity and elicit a marked remodelling of the isoform repertoire." (PMID 30975994, 2019). "To extrapolate the role of TLR7 in EV71-induced neuropathogenesis to human infections, we performed the histological analysis in six human brain specimens." (PMID 31730654, 2019). "Mice deficient in endosomal TLR signalling (TLR3, TLR7 and TLR9) showed heightened susceptibility to infection with a neuroadapted SINV." (PMID 30909385, 2019). "We found that the PFU value of EV71 was robustly high from day 2 to 3 post-infection, and then declined from day 5 to 7 post-infection in the brain tissues of both infected WT and TLR7-/- mice." (PMID 31730654, 2019). "Total anti-RABV IgG levels in WT mice were 2 to 3-fold higher than those in TLR7−/− mice at 2, 3, and 4 weeks post infection (w.p.i.)." (PMID 30906301, 2019).
infection (continued). "Our results revealed that IL-1β mRNA level was higher in the infected cerebral cortex of WT mice on 3 days post-infection as compared with infected TLR7-/- mice." (PMID 31730654, 2019). "Further, endosomal adaptor HRS has been shown to play a regulatory role in the assembly of TLR7 complex at endosomes during EV-A71 infection, leading to protection against EV-A71 infection." (PMID 31787104, 2019). "Many viruses can induce the up-regulation of viperin during infection, and viperin is shown to have critical roles in inhibiting viral replication and facilitating TLR7- and TLR9-mediated production of IFN-I, yet its function can be dampened by some viruses." (PMID 31921110, 2019). "We observed that VSV-luciferase activity in TLR7−/− pDC was significantly reduced compared to Wt pDC after 6 h of infection." (PMID 30930901, 2019). "In light of the role of the monocytic compartment seen previously, we next assessed the role of Tlr7 in S. Typhimurium survival after infection of BMMs." (PMID 29616197, 2018). "All the WT mice were highly sensitive to infection and reached humane endpoints by days 5–7, against only one Tlr7−/− mouse by day 13, the day at which the experiment was stopped and all the Tlr7−/− mice were culled." (PMID 29616197, 2018). "The CH strain downregulated TLR3 and TLR7 during the early stage of infection (24 and 36 hpi); this downregulation was most obvious at 36 hpi." (PMID 29700351, 2018). "Toll like receptor 7 was upregulated during the infection with both parasites, whereas TLR 1-5 and 8 where exclusively upregulated in P. falciparum." (PMID 30248353, 2018). "Previous results have been indicated that chicken origin TLR7 can be recognized by viral ssRNA, which is largely released during the infections with chicken influenza virus." (PMID 29670609, 2018). "IL-27 was enhanced rapidly by DCs and other myeloid cells upon infection, with pDCs in particular upregulating IL-27 transcripts in a TLR7-dependent fashion." (PMID 29593047, 2018). "In contrast to the liver tissue, significant upregulation of TLR3, TLR4, and TLR10, but downregulation of TLR7, characterized hepatocytes derived from livers of animals with resolved AH accompanied by secondary occult infection." (PMID 30581424, 2018). "Overall, our data suggest that the GLA-SE adjuvanted sH1N1 vaccine provides superior protection in young mice by clearing influenza virus early after infection, and through maintenance of AMs and TLR7 expression levels in the early infection phase." (PMID 29515589, 2018). "M6PR and TLR7 expression was markedly decreased in 16HBE cells after EV71 or CA16 infection, but M6PR expression recovered significantly, concomitant with an increase in TLR7, after treatment with 3-MA." (PMID 29052054, 2018). "GS-9620 is a potent TLR7-selective agonist that induces antiviral immunity and clearance of infection in preclinical models of hepatitis B virus infection." (PMID 28179531, 2017). "In contrast, in the current study an unexpected suppressive effect in the TLR7 gene expression was observed only during the early phase of IBV B isolate infection (1dpi), as the transcripts of this gene were found 5 times downregulated." (PMID 28199419, 2017). "In this study, we focused on the stimulatory activity of B. abortus RNA, as well as the role of TLR3 and TLR7 in cell signaling pathways and host protection against infection." (PMID 28167945, 2017). "During the early infection, TLR7 and MDA5 were also highly up-regulated from 2 dpi to 6 dpi in both virulent and attenuated strain-infected kidneys." (PMID 28038465, 2017). "Infection of pDC with VSV is sensed via the toll-like receptor 7 (TLR7), which mediates a maturation and activation of pDCs and can further lead to priming of CD8+ T cells." (PMID 28536351, 2017). "It is interesting to note that these sensors often work in tandem with each other and/or TLR7 to respond to infection." (PMID 28928743, 2017).
infection (continued). "In this study, TLR-7 was upregulated against the infection of DHAV-1, although the upregulation was mainly within 4 days after infection, as IgG levels were negatively correlated with the expression of TLR-7." (PMID 29201029, 2017). "WT and Tlr7−/− mice were challenged by intranasal infection with 1 × 103 CFU (approximately 2.5× the 50% lethal dose [LD50]) of Y. pestis CO92." (PMID 28847850, 2017). "Other cytokines and PAMPs released during inflammation as a result of infection or disease likely play a role in the regulation of constitutive and inducible TLR7 expression." (PMID 28928743, 2017). "Our results suggest that upon infection of WT DCs with B. abortus, TLR7 traffics to LAMP-1+ endosomes, spreading throughout the cells." (PMID 28167945, 2017). "TLR7 expression was determined by qRT-PCR at different time points (12, 24, 48, and 72 h) following infection." (PMID 28265274, 2017). "In this study, TLR-7 expression was highly upregulated by day 2 after infection, but showed a decreasing tendency which was inverse to the increase in viral titers." (PMID 29201029, 2017). "Alveolar macrophages are the primary source of increased IL-33 levels during infection, and an in vitro stimulation of these cells with a TLR7 agonist induces IL-33 expression." (PMID 28205524, 2017). "Subsequent acidification of the phagosome is required for IFN-β expression by DCs following infection with S. suis, suggesting that bacterial processing via hydrolytic degradation is essential for the liberation of TLR7 and TLR9 ligands." (PMID 28894449, 2017). "Upon infection, agonist stimulation, or damage/apoptosis to neighboring cells, ligands must enter the endosome to trigger TLR7 activation." (PMID 28928743, 2017). "Overall, the phenotypic observations suggest a bifunctional, tissue-specific role for TLR7 in the host response to Y. pestis CO92 infection." (PMID 28847850, 2017). "We therefore also compared IFN-β expression levels between WT and Tlr7−/− BMDMs following infection with the S. aureus Δspa mutant." (PMID 28847850, 2017). "vvIBDV infection of DT40 cells led to the downregulation of TLR7 and upregulation of TLR15; these results were further confirmed by TLR expression profiles in the bursa of DT40 cell-derived vvIBDV-inoculated chickens." (PMID 28086922, 2017). "In our laboratory, we demonstrated that ALV-J infection significantly increased TLR7 expression in chicks followed by MDA5 when the infection progressed to tumorigenesis." (PMID 28066434, 2016). "Several RNA virus associated PRRs, including DDX58, IFIH1, TLR7, and TLR8, were regulated according to infection status, being up-regulated at 24 h pi, and showing little or negligible change in expression during the rest of the study." (PMID 26893019, 2016). "Collectively our data indicate the critical protective role of TLR7/9 signaling at both a cellular and organismal level during infection with a common fungal pathogen of humans." (PMID 27459510, 2016). "The transcription of TLR1, TLR5 and TLR7 then rose again to a certain extent at the chronic stage of infection (T3)." (PMID 27661612, 2016). "The majority (70–90%) of IFNAR-/- and TLR7/9-/- mice succumbed by 14 days post-infection (dpi), whereas 90–100% of the wild-type mice survived the course of the experiment." (PMID 27459510, 2016). "Meanwhile, the expression level of TLR7 was upregulated throughout the period of infection, except at 36 h p.i. induced by NH-10, in response to infection with both viruses or treatment with poly(I:C)." (PMID 26975566, 2016). "Treatment of MDMs with the TLR7 agonist gardiquimod induced a block to infection of co-cultured, activated PBMC and treatment of activated PBMC with agonists specific for TLRs 3, 7, 8 and 9 blocked HIV-1 replication." (PMID 27905985, 2016). "TLR7 activation results in autophagy induction and thus, during early infection ssRNA originating from RSV can induce autophagy via TLR7." (PMID 28018859, 2016).